FXN (frataxin)
Diseases named in the same sentence as FXN in open-access papers (continued):
Sharing a sentence is not in itself a finding about the gene and the disease.
Friedreich ataxia (continued). "In this article we present non-clinical studies evaluating the pharmacology of nomlabofusp, including in a murine striated muscle tissue frataxin knockout model of Friedreich's ataxia." (PMID 40562976, 2025). "Such SynGRs were effective in recruiting BET proteins, including BRD4, to frataxin gene and restoring frataxin transcription in cells derived from Friedreich’s ataxia patients." (PMID 40149571, 2025). "Friedreich’s Ataxia (FA) is a rare, inherited ataxia resulting from GAA triplet expansions in the first intron of the Frataxin (FXN) gene, which encodes a mitochondrial protein involved in the incorporation of iron into iron–sulfur clusters." (PMID 40303283, 2025). "The two most common ARCAs are Friedreich Ataxia (FRDA), resulting from an expanded intronic GAA repeat on both alleles of the FXN gene, and RFC1‐mediated ataxia, due to biallelic intronic AAGGG repeats." (PMID 40464291, 2025). "Together, the findings from these non-clinical studies demonstrate that nomlabofusp exposure increases human frataxin in Friedreich's ataxia-relevant tissues and provide evidence of pharmacologic effects." (PMID 40562976, 2025). "Friedreich’s ataxia is an inherited neurodegenerative disorder caused by GAA triplet repeat expansions in the FXN gene, which lead to frataxin deficiency." (PMID 40963932, 2025). "Although the most common form of autosomal recessive ataxia, Friedreich ataxia (FA), is caused by GAA expansion of the Frataxin (FXN) gene in most of the cases, the majority of AR ataxias are caused by SNV, small deletions or duplications." (PMID 40584247, 2025). "Redox homeostasis is impaired in Friedreich’s Ataxia (FRDA), a neurodegenerative disease caused by the decreased expression of the mitochondrial protein frataxin." (PMID 40308559, 2025). "FXN is harbored in a mid-late replicating locus, and its replication profile has been well characterized owing to its involvement in Friedreich’s Ataxia 9,37,38." (PMID 39975922, 2025). "In this study, we extend these findings by showing that targeting repeat-expanded chromosomal DNA with anti-gene oligonucleotides leads to an increase in Frataxin mRNA and protein levels in cells derived from Friedreich’s ataxia patients." (PMID 40487352, 2025). "The optic nerves in Friedreich’s ataxia suffer from defective mitochondrial metabolism akin to LHON, but patients also develop cardiomyopathy and ataxia due to frataxin deficiency in those tissues." (PMID 40332750, 2025). "Friedreich’s ataxia results from pathogenic variants in the nuclear-encoded FXN gene, which produces frataxin—a mitochondrial protein crucial for the assembly of iron-sulfur clusters." (PMID 41149856, 2025). "Nomlabofusp is a cell penetrant peptide-based recombinant fusion protein designed to enter cells and deliver human frataxin into the mitochondria of adults and children with Friedreich's ataxia." (PMID 40562976, 2025). "Friedreich’s ataxia is a progressive, autosomal recessive ataxia caused, in most cases, by homozygous expansion of GAA⋅TTC triplet-repeats in the first intron of the Frataxin gene." (PMID 40487352, 2025). "TALE-VP64 targeting 14-bp DNA sequence in the promoter of FXN was created, and it increased FXN mRNA levels by 2- to 3-fold in 293FT cells and by 2-fold in human fibroblasts derived from human Friedreich’s ataxia patients." (PMID 40650152, 2025). "One notable example within the realm of ARAs is Friedreich’s ataxia (FRDA), an autosomal recessive ataxia linked to GAA triplet repeat expansion in the frataxin (FXN) gene." (PMID 40291849, 2025). "For Friedreich's ataxia therapies targeting increased frataxin levels, monitoring frataxin itself is the most direct approach." (PMID 38846537, 2024). "Friedreich ataxia is the most common of the inherited ataxias, caused mainly by homozygous GAA triplet repeat expansion in intron 1 of the FXN gene encoding for frataxin, a mitochondrial protein involved in iron metabolism." (PMID 39339713, 2024).
Friedreich ataxia (continued). "Carriers and Friedreich's ataxia patients exhibit reduced frataxin levels when compared with controls." (PMID 38846537, 2024). "This study delves into the consequences of mitochondrial frataxin (FXN) depletion, the primary cause of Friedreich’s ataxia (FRDA), a debilitating neurodegenerative condition characterized by impaired coordination and muscle control." (PMID 38631900, 2024). "Friedreich’s ataxia (FA) (OMIM # 229300), a rare degenerative autosomal recessive disorder, is caused by silencing of FXN on chromosome 9 by extension of the GAA triplet in its first intron." (PMID 39736600, 2024). "Friedreich ataxia (FRDA) is the most common single-gene autosomal recessive ataxia disease, caused by frataxin (FXN) gene mutation, with a prevalence estimated at about 1 to 50,000 and a calculated carrier frequency of ≈ 1 into 120 in Caucasian populations." (PMID 39191875, 2024). "In contrast, FXN GAA expanded repeats in Friedreich’s ataxia patients show an expansion bias in the cerebellum, and skeletal muscle in Myotonic Dystrophy Type 1 present with much larger DMPK CTG expansions." (PMID 38396267, 2024). "Mitochondrial peptidases also play a role in the maturation of Frataxin, the protein affected in Friedreich’s ataxia." (PMID 37576821, 2023). "Friedreich ataxia, the most frequent recessive HCA, is caused by a biallelic intronic GAA expansion in the FXN gene, and ataxia–telangiectasia (the second most common recessive HCA in some series) arises from point mutations in the ATM gene." (PMID 37048110, 2023). "Friedreich’s ataxia patients most commonly exhibit an expansion of a GAA trinucleotide repeat within an Alu element within the first intron of the frataxin gene." (PMID 37629187, 2023). "The low abundance (less than 70%) of a mitochondrial iron-binding protein Frataxin (FXN), which is involved in iron–sulfur cluster ([Fe–S]) biosynthesis, leads to a severe neurodegenerative disorder, Friedreich ataxia (FRDA)." (PMID 36836919, 2023). "The YG8sR mouse is a model of Friedreich ataxia, having both mouse frataxin genes knockout but containing a human frataxin transgene with 250–300 GAA repeats." (PMID 37628705, 2023). "To further verify the importance of the Fe-S cluster in NCOA4 turnover, we used other Fe-S cluster deficiency models: lymphocytes derived from Friedreich’s ataxia (FRDA) patient and YG8R mice with frataxin (FXN) deficiency." (PMID 38159858, 2023). "One of these diseases is Friedreich's ataxia (FRDA): a rare, autosomal recessive degenerative disease caused by the expansion of GAA•TTC repeats in the first intron of the frataxin gene (FXN)." (PMID 37216608, 2023). "Friedreich’s ataxia, an autosomal recessive disorder, is caused by tandem GAA nucleotide repeat expansions in intron 1 of the frataxin gene." (PMID 37006329, 2023). "Friedreich’s ataxia (FRDA) is an autosomal, recessive, inherited neurodegenerative disease caused by the loss of activity of the mitochondrial protein frataxin (FXN), which primarily affects dorsal root ganglia, cerebellum, and spinal cord neurons." (PMID 37238963, 2023). "Despite the reversal of the repressive epigenetic state at the FXN locus and the restoration of FXN expression, isogenic control neurons retain many features of Friedreich ataxia neurons." (PMID 36865673, 2023). "The most common form of recessive ataxia in human is Friedreich ataxia (FRDA), which affects ≈ 1:30,000–50,000 of the population worldwide and is caused by mutations in the FXN-gene." (PMID 35061740, 2022). "Friedreich’s ataxia (FRDA; OMIM #229300) is an autosomal recessive disorder caused by frataxin mutations." (PMID 35625641, 2022). "Friedreich ataxia (FRDA) is a neurodegenerative disorder leading to dorsal root ganglia degeneration, caused by mutations of the FXN gene, which encodes frataxin (FXN), a mitochondrial protein found in the IMM." (PMID 36092728, 2022).
Friedreich ataxia (continued). "Friedreich ataxia (FRDA) is caused by a GAA trinucleotide expansion in intron 1 of FXN, which encodes the frataxin protein (FXN)." (PMID 35668433, 2022). "The aberrant expression of Suv4-20h proteins has also been described in neuromuscular disorders such as Friedreich’s ataxia (FRDA), which is caused by the decreased expression of the frataxin gene (FXN)." (PMID 35563127, 2022). "Friedreich’s ataxia (FRDA) is the most frequently inherited recessive ataxia, and it is ascribed to severe deficiency of frataxin, a nuclear-encoded mitochondrial protein involved in iron–sulfur cluster (ISC) protein biogenesis and iron homeostasis." (PMID 36393859, 2022). "Friedreich’s ataxia, a neurodegenerative condition secondary to the FRDA gene mutation that causes reduced levels of frataxin, the mitochondrial protein involved in iron regulation." (PMID 36579590, 2022). "Epigenetic silencing in Friedreich ataxia (FRDA), induced by an expanded GAA triplet-repeat in intron 1 of the FXN gene, results in deficiency of the mitochondrial protein, frataxin." (PMID 35322126, 2022). "Mutations in FXN cause Friedreich ataxia (FA), one of the best known recessively inherited ataxias." (PMID 35203288, 2022). "Frataxin, an essential protein highly conserved in most organisms, is involved in the neurodegenerative disease Friedreich's ataxia (FRDA) in humans." (PMID 35474632, 2022). "Friedreich’s ataxia (FRDA) is the most frequent autosomal recessive (AR) inherited ataxia, caused by a defect in the frataxin (FXN) gene on chromosome 9 (9q13-q21.1,57)." (PMID 34941648, 2021). "For instance, in Friedreich ataxia, which is caused by an expanded GAA repeat in the first intron on both alleles of the FXN gene, levels of instability found in tissues from an 18-week-old fetus were very low compared to adult-derived tissues." (PMID 33983118, 2021). "Truncation of the FXN C-terminus results in significant destabilization of the protein and a severe Friedreich’s ataxia phenotype in eukaryotes." (PMID 34199378, 2021). "A mouse model of Friedreich ataxia with a striated-muscle specific frataxin knockout showed an increase in expression of the CLPP and LON proteases associated with a decrease in mitochondrial Fe-S proteins." (PMID 34280433, 2021). "Approximately 95% of Friedreich's ataxia patients are homozygous for an unstable GAA expansion in the FXN gene." (PMID 32813850, 2020). "For example, the incidence of diabetes in Friedreich’s ataxia (FA) ranges between 8–32% of patients, but the risk of developing is directly correlated to the number of GAA repeats in the frataxin (FXN) gene." (PMID 32369911, 2020). "Reduced levels of frataxin (FXN), an essential protein found in sensory neurons, is associated with Friedreich’s ataxia patients." (PMID 32580326, 2020). "A similar involvement of oxidative stress in neurodegeneration was also proposed for Friedreich ataxia, in light of the abnormal levels of antioxidant enzymes found in the cerebella of frataxin-depleted mice." (PMID 32168822, 2020). "They include: myotonic dystrophy type 1 (DM1), caused by a CTG expansion in the DMPK1 gene, Huntingdon's disease (HD), caused by a CAG expansion in the huntingtin gene (HTT) and Friedreich's ataxia, caused by GAA expansion in frataxin (FXN)." (PMID 33099215, 2020). "In Friedreich’s ataxia, frataxin protein level is used as a biomarker reflecting an early event in pathophysiology, as it was shown to be reduced in patients in consequence of the intronic repeat expansion leading to impaired transcription of the FXN gene." (PMID 32002649, 2020). "It is noteworthy that reduced FXN expression can lead to Friedreich ataxia (FRDA), a severe genetic neurodegenerative disease." (PMID 32131492, 2020). "Another genetic form of ataxia is Friedreich ataxia (FA), caused by an unstable GAA expansion in the first intron of the FXN gene, which results in decreased levels of a protein called frataxin." (PMID 32168822, 2020).
Friedreich ataxia (continued). "Friedreich's ataxia (FRDA) is a rare genetic disorder affecting the FXN gene which produces the protein frataxin within the mitochondria of the cells." (PMID 32731306, 2020). "As lack of frataxin is thought to be the pathomechanism driving all further steps in the pathogenesis of Friedreich’s ataxia, several therapeutic approaches are aiming to increase transcription of the FXN gene." (PMID 32002649, 2020). "In eukaryotic cells, [2Fe-2S] cluster assembly in the mitochondria is activated by FXN and the decrease in FXN functionality or expressions results in Friedreich’s Ataxia." (PMID 32957566, 2020). "Another example of TNR associated disease is Friedreich’s ataxia, which is connected with an unstable (GAA)n·(TTC)n trinucleotide repeat expansion in the first intron of the frataxin gene (FXN, chromosome 9q13)." (PMID 31159174, 2019). "An in vivo mouse model of Friedreich Ataxia showed partial increased expression of the frataxin (FXN) gene when GAA trinucleotide repeats were deleted from intron 1 with Cas9." (PMID 30669625, 2019). "Friedreich’s Ataxia (FRDA) is a rare multisystemic disorder caused by homozygous GAA triplet repeat expansion in the FXN, encoding for the mitochondrial protein frataxin (FXN)." (PMID 31842377, 2019). "In Friedreich’s ataxia, expansions of unstable nucleotide repeats in the FXN gene result in reduced expression of frataxin, a protein thought to act as molecular chaperone in iron-sulfur clusters and heme biosynthesis as well as iron storage site." (PMID 30881284, 2019). "A prime example is expanded GAA•TTC repeats in the Frataxin gene in Friedreich’s ataxia, which can form an intramolecular triplex (H-DNA)." (PMID 31098852, 2019). "In the case of Friedreich's ataxia, this results in transcriptional silencing of the Frataxin (FXN) locus." (PMID 30478192, 2019). "For example, Huntingtin (HTT; Huntington's Disease), Frataxin (FXN; Friedreich Ataxia), and Ataxin 1/2 (ATXN1/ATXN2; Spinocerebellar Ataxias) all have GC-rich trinucleotide expansion tracks that form R-loops in vitro and associate with disease progression." (PMID 31225499, 2019). "Our understanding of mitochondrial homeostasis and metabolism is also broadened by the discovery of novel mutations causing these neurodegenerative diseases, with an appropriate example being the identification of the role of frataxin in Friedreich's ataxia." (PMID 31057691, 2019). "Double-strand RNA (dsRNA) has been examined for activating FXN gene expression in Friedreich’s ataxia patient–derived fibroblasts." (PMID 31098852, 2019). "It is of note that reduced FXN expression leads to Friedreich ataxia (FRDA), a severe genetic neurodegenerative disease." (PMID 30529286, 2018). "This permitted selection of 3 plTALEVP64s and 2 plTALESunTag that increased FXN gene expression by up to 19-fold in different Friedreich ataxia (FRDA) primary fibroblasts." (PMID 30195758, 2018). "Friedreich ataxia (FA) is a rare disease caused by deficiency of frataxin, a mitochondrial protein." (PMID 28980774, 2018). "Some of these compounds significantly increase mitochondrial biogenesis and frataxin levels in cultured Friedreich’s ataxia cells." (PMID 30225325, 2018). "These “in vitro” results combined with the data provided by tests performed “in vivo” using mice models of Friedreich ataxia suggest that TAT‐MTScs‐frataxin can be considered a candidate for the disease therapy." (PMID 28980774, 2018). "Friedreich’s ataxia (FA) is an autosomal recessive neurodegenerative disorder, which results primarily from reduced expression of the mitochondrial protein frataxin." (PMID 29447225, 2018). "Decreased expression of frataxin protein is responsible for the devastating rare genetic disease of Friedreich’s ataxia." (PMID 30451920, 2018).
Friedreich ataxia (continued). "Friedreich ataxia (FRDA) is an autosomal recessive neuro- and cardio-degenerative disorder caused by decreased expression of frataxin, a protein that localizes to mitochondria and is critical for iron-sulfur-cluster (ISC) assembly." (PMID 29568068, 2018). "The GAA triplet expansion of the FXN gene in Friedreich ataxia alters nucleosome positioning and reduces transcription by making the start site not accessible." (PMID 30591019, 2018). "Although very early after the discovery of frataxin as the gene that was responsible for Friedreich’s Ataxia, it was established that iron homeostasis was altered by frataxin deficiency, the specific function of this protein remains controversial." (PMID 30235822, 2018). "Two regulatory proteins are CyaY (frataxin), which is the protein involved in Friedreich's ataxia in humans, and IscA, which is thought to be an alternative scaffold protein." (PMID 28664160, 2017). "Patients suffering from the progressive neurodegenerative disease Friedreich’s ataxia have reduced expression levels of the protein frataxin." (PMID 29200434, 2017). "We have used siRNA-induced knockdown of frataxin in SH-SY5Y cells as an in vitro cellular model for Friedreich’s ataxia." (PMID 28456899, 2017). "FRDA patients live with a reduced and insufficient amount of frataxin protein; thus, the main goal of a specific therapy for Friedreich ataxia would be to restore physiological frataxin levels." (PMID 28228265, 2017). "Another example is Friedreich ataxia (FRDA), a neurodegenerative disease caused by failure to assemble Fe‐S clusters due to defects in the mitochondrial iron chaperone frataxin." (PMID 28449241, 2017). "Depletion of RNF126 in cells derived from FRDA patients promotes accumulation of mature frataxin, pointing toward this E3 ligase as a new potential therapeutic target for Friedreich ataxia." (PMID 28228265, 2017). "Friedreich’s ataxia (FRDA), the most commonly inherited ataxia in populations of European origin, is a neurodegenerative disorder caused by a decrease in frataxin levels." (PMID 27433942, 2016). "Friedreich Ataxia (FRDA) is the most common form of hereditary ataxia and it is due to recessive mutations in the FXN gene, which encodes for a mitochondrial protein involved in the biosynthetic pathways of iron-sulphur clusters." (PMID 27696015, 2016). "Dorsal root ganglia (DRG) are highly vulnerable to frataxin deficiency in Friedreich ataxia (FA), an autosomal recessive disease due to pathogenic homozygous guanine-adenine-adenine trinucleotide repeat expansions in intron 1 of the FXN gene (chromosome 9q21.11)." (PMID 27142428, 2016). "Genomic DNA was extracted, followed by the screening of GAA repeat expansion in FXN gene to exclude Friedreich’s ataxia." (PMID 27644330, 2016). "Similar neurodegenerative events have been described to occur in Friedreich's ataxia, where deficiency of the ISC–iron chaperone, frataxin, causes shortages of the ISC‐dependent respiratory complexes that lead to energy deficiency." (PMID 27516453, 2016). "Friedreich’s ataxia (FRDA), the most common inherited ataxia in the Caucasian population, is a multisystemic disease caused by a significant decrease in the frataxin level." (PMID 26158631, 2015). "The genetic defect in Friedreich’s ataxia (FRDA) is the hyperexpansion of a GAA•TTC triplet in the first intron of the FXN gene, encoding the essential mitochondrial protein frataxin." (PMID 25798128, 2015). "Unfortunately, the important genetic instability of frataxin knockdown cell lines, such as murine fibroblast models for Friedreich's ataxia, is a severe limitation in a high-throughput drug screen." (PMID 26523199, 2015). "The most common mutation was the (GAA)n expansion in the first intron of the FXN (frataxin) gene which is responsible for the Friedreich ataxia phenotype, present at the homozygous state in 49 (44.54 %) patients representing 31 (40.79 %) families." (PMID 26068213, 2015).